IL6 (interleukin 6)
Diseases named in the same sentence as IL6 in open-access papers (continued):
Sharing a sentence is not in itself a finding about the gene and the disease.
tumor (continued). "There is mounting evidence showing that blocking of IL-6 trans-signaling not only inhibits tumor initiation in animal models but can also interfere with the growth of established tumors." (PMID 31491838, 2019). "Whatever the mechanism involved, the final consequence is the increment of IL-6 expression and the induction of its connate pathway, which has been involved with tumor promotion." (PMID 31396215, 2019). "The immune system environment is characterized by high levels of stimulatory cytokines, such as interleukin (IL)-6, tumor necrosis factor-α (TNF-α), and eotaxin produced by nascent tumor cells and/or by reactive tumor-associated immune cells." (PMID 30814315, 2019). "Only those PSCs located away from tumor cells, denoted as “inflammatory CAFs (iCAFs)”, were proficient in secreting pro-stemness IL-6, CXCL-1 and CXCL-2 through activation of IL-1α–Janus kina (JAK)–STAT signaling." (PMID 31108941, 2019). "Increased IL-6 expression in tumor tissues from EOC patients with disease progression predicts chemotherapy resistance and poor patient survival." (PMID 31817625, 2019). "To elucidate the correlation between IL-6 or IL-8 and clinical characteristics, we performed an IHC array to analyse IL-6/IL-8 expression in 103 pairs of tumours and matched adjacent tissues of patients with ESCC." (PMID 31324197, 2019). "In the mice bearing knock-down B16F10 tumors, the frequency of IL-21+ and IL-10+ CD4+ T cells in the tumor draining lymph node and tumor tissue and the serum IL-6 level were significantly reduced as compared to those in the mice bearing control tumors." (PMID 31300052, 2019). "This study also showed a close relationship between detectable IL-6 and tumor burden, and the mean serum level of IL-6 in patients with mUICC stage IV was significantly higher than that of patients with mUICC stage I-III." (PMID 30824840, 2019). "As an example, the presence of TNF, IL-1, IFN-γ and hypoxic conditions in the TME induces the secretion of proangiogenic and immune suppressive factors (including EGF, PDGF, fibroblast growth factor 2, FGF-2, VEGF, IL-6 and IL-10) allowing tumor proliferation." (PMID 30781344, 2019). "These authors demonstrate that HER2 expression in the tumor drives a positive feed-forward activation loop, inducing the expression of IL-1α and IL-6." (PMID 31231372, 2019). "It was also reported that the interaction of neutrophils with tumor cells promoted GC cell migration and invasion through a pathway involving IL-6." (PMID 31238937, 2019). "This inhibition of dendritic cell differentiation is mediated through the induction of IL-6 by tumor-derived exosomes." (PMID 31555295, 2019). "STAT3 activation in tumor cells leads to increased production of immunosuppressive cytokines, including interleukin-6 (IL-6), IL-10, vascular endothelial growth factor (VEGF), and transforming growth factor-b1 (TGF-β1)." (PMID 31671769, 2019). "Another important pro-inflammatory cytokine IL-6, present in tumor microenvironments, is involved in the EMT and in the acquisition of a stem-like phenotype of cancer cells." (PMID 30691081, 2019). "Hippocampal (U = 75, p < 0.05) and frontal cortex (U = 48, p < 0.005) Il-6 responses 4 h post-LPS were reduced in tumor-bearing mice relative to tumor-free controls; a similar trend was observed in the hypothalamus (p = 0.06)." (PMID 30679700, 2019). "Macrophages associated with hepatocellular carcinoma have a high expression of epidermal growth factor receptor (EGFR), which induces IL6 signaling pathway, and hepatocyte proliferation being thus considered a tumor-promoting factor." (PMID 31921146, 2019).
tumor (continued). "IL-6 was also found to simultaneously induce CpG promoter methylation of several putative tumor suppressor genes including GATA5, PAX6, and CHFR, inhibiting their expression in oral squamous cell carcinoma cell lines." (PMID 31557902, 2019). "Cytokine IL-6, which has a dual role in the anti-tumor immunity, activates signaling proteins Stat1 and Stat3 in addition to its other functions." (PMID 31709183, 2019). "We have recently demonstrated that short-term exposure of osteoblasts to pH 6.8 promotes the expression of factors that foster tumor progression, such as interleukin 6 (IL6), interleukin 8 (IL8), and the chemokine (C-C motif) ligand 5 (CCL5)." (PMID 30825056, 2019). "PGE2, a key factor produced in chronic inflammation and tumor, potentiate GM-CSF/IL-6-dependent induction of M-MDSC, their suppressive potential and their capacity to induce the Th2 response in vitro." (PMID 30936876, 2019). "In particular, interleukin (IL)-6, leptin, and adiponectin secreted by fat cells play an important role in tumor growth." (PMID 30646912, 2019). "Based on our previous report, elevated anti-inflammatory cytokines such as IL-6, IL-10, and TGF-β in tumor-associated ascites are related to tumor progression." (PMID 31753019, 2019). "Pro-tumor molecules such as IL-6, IL-8, and HGF secreted by CA-MSCs or their receptors can be blocked to circumvent the pro-tumor effects of the MSC." (PMID 31547627, 2019). "In the current paper, we investigated the function of tumour infiltrating T cells at various stages after tumour transplantation in a TC-1 tumour mouse model and showed that caerin 1.1 and 1.9 were able to stimulate the secretion of IL-6 by TC-1 cells." (PMID 31277636, 2019). "IL-6 is one of the inflammatory cytokines involved in tumor growth by evoking anti-apoptotic response and stimulating tumor development." (PMID 30642295, 2019). "The results showed that the combined ginkgetin–resveratrol treatment significantly reduced the levels of TNF-α and IL-6 cytokines in 5-FU-treated tumor tissues, which were consistent with the expression of COX-2 protein." (PMID 31757048, 2019). "A correlation was seen between high ACTA2/IL6 co-expression and the tumor grade (*P = 0.0179) and lymph node metastasis (*P = 0.0281)." (PMID 30744595, 2019). "Paraneoplastic thrombocytosis was driven by IL-6 and hepatic thrombopoietin, both of which stimulated tumor cell proliferation and migration; however, the mechanism is not clearly understood." (PMID 30630439, 2019). "Tumor cell-derived mediators such as TNFα, IL-6, TWEAK, myostatin and extracellular vesicle HSPs have been postulated to play a role in the pathogenesis of cancer cachexia." (PMID 31851697, 2019). "IL-6 mRNA expression showed the tendency to increase in the tumor control group and to decrease by ajoene extract treatment." (PMID 31717643, 2019). "In the tumor microenvironment, IL-6 can be produced in response to tumor cells, tissue necrosis, and tissue inflammation." (PMID 31272506, 2019). "For example, tumor-derived cytokines, including IL-6 and IL-1β, as well as cytokines released from activated T cells, such as IL-4 and IL-10, develop common myeloid progenitor cells into MDSCs." (PMID 31048856, 2019). "M2d macrophages induced by adenosine, leukemia inhibitory factor (LIF) and IL-6 are believed to induce angiogenesis to regulate tumor progression and enhance tumor survival." (PMID 31192126, 2019). "IL-9 at D3 and D7 seemed to be related to anti-tumor effect and IL-6 at D7 and D60, and IL-22 at D60 was related to regenerative but not pro- or anti- inflammatory function." (PMID 31751357, 2019). "IL‐6 levels secreted in media and IL‐6 mRNA levels in tumor tissues, and expression of p‐STAT3 is upregulated in cells with overexpression of LNRRIL6 and is downregulated in LNRRIL6 knockdown cells." (PMID 31246342, 2019). "Exosomes in turn transferred miR-let-7b to macrophages to inhibit the expression of pro-inflammatory IL-6, thus weakening tumor inflammation." (PMID 31555295, 2019).
tumor (continued). "The IL-6/JAK/STAT3 pathway contributes to treatment resistance promoting tumor cell survival after targeted anticancer drugs or ADT." (PMID 31143708, 2019). "Bone marrow derived MSCs (BM-MSC) when exposed to tumor conditioned medium can transform into CAFs and stimulate tumor growth via secretion of inflammatory cytokine IL-6 in the tumor stroma." (PMID 31921870, 2019). "We suggested that chronic infection by P. gingivalis caused secretion of cytokines such as IL6 to initiate OSCC and to activate tumorigenic transcription factors such as STAT1 for tumor progression." (PMID 30847302, 2019). "These included LPS/IL-1 mediated inhibition of RXR function, TNFR2 signaling, metastasis signaling, and tumor-promoting inflammation signaling such as that mediated by IL-10, IL-6, and NF-κB (all P < 0.001)." (PMID 31001473, 2019). "Circulating IL-6, IL-8, and IL-10 levels were concomitantly decreased along with tumour shrinkage after 24 weeks of treatment." (PMID 30922248, 2019). "Tumor-associated macrophages (TAMs), neutrophils and CAFs in the TME are the major cell types that secrete IL-6 and IL-1β and are responsible for the activation of STAT3 in tumor cells." (PMID 30927928, 2019). "Since the major source of IL‐6 is the tumor stroma, STAT3 signaling represents a signaling pathway that is driven by the stroma during the PDA progression." (PMID 31609088, 2019). "Oncogenic signaling pathways such as Ras/Raf/MEK or PI3K can also enhance the production and secretion of IL-6, which acts in a paracrine manner to promote tumor growth." (PMID 31557902, 2019). "Stromal VCAN expression is induced by TGFβ and IL6 and has been shown to regulate processes like tumour growth and invasion." (PMID 31336942, 2019). "Constitutive activation of IL-6 signaling has been shown to establish a microenvironment for tumor initiation and progression." (PMID 31771617, 2019). "In a Drosophila melanogaster malignant tumor model, early-stage tumor growth and invasion are genetically dependent upon tumor necrosis factor and interleukin-6 mediated autophagy within the local tumor microenvironment." (PMID 30741926, 2019). "The exercise-induced epinephrine surge and IL-6 suppress tumor growth and development through NK cell mobilization and redistribution." (PMID 30688660, 2019). "In tumor tissue, the number of FoxP3+ Tregs was positively correlated with IL-6 expression and negatively correlated with IL-2 and TNF-α expression (R2 = 0.0720, P = 0.0161; R2 = 0.1030, P = 0.0037; and R2 = 0.0507, P = 0.0446, respectively)." (PMID 31417548, 2019). "Results are as follows, The high expression of NRP1 in the A549RR group boosted the mRNA and protein levels of IL-17A and IL-6 in tumor tissue, respectively." (PMID 31417646, 2019). "In the same way, the type of tumor removal surgery, as well as changes in weight and pain score, were possible predictors of change in IL-6 concentration after using the app." (PMID 31414667, 2019). "IL-6, IL-6sR, sTNFRI, and IL-11 are pro-inflammatory cytokines that contribute to angiogenesis, cell proliferation, tumor cell survival, exhaustion of effector T cells, and therapeutic resistance." (PMID 31510045, 2019). "Currently, it is believed that thrombopoietin is secreted by tumour cells, just as interleukin-6 is." (PMID 30824727, 2019). "The deficit of IL-6 leads to a diminution of the generation and the function of MDSCs, a diminution of their T cell suppressor function, leading to a diminution of tumor progression and to its metastatic potent." (PMID 30708988, 2019). "Their results also indicated that the increased expression of CHOP activated the function of C/EBPβ/IL-6 axis which enhanced the immunosuppressive activity of MDSCs in inflamed tumor milieu." (PMID 31129755, 2019). "In conclusion, salivary IL-6 mRNA is a robust biomarker for OSCC in the Hungarian population in comparison with tumor-free control persons." (PMID 31766212, 2019).
tumor (continued). "For instance, IL-37 reduces the secretion by both immune cells and tumor cells of IL-6, IL-1β and tumor necrosis factor alpha, cytokines known to play a role in tumor progression." (PMID 31231372, 2019). "An increased frequency of CD4+ and CD8+ T cells and a decreased level of IL-6 in tumor tissue were also found." (PMID 30959898, 2019). "In murine CD11b+ myeloid DC precursors, tumor EVs inhibited the differentiation of DCs via enhanced expression of interleukin 6 (IL-6)." (PMID 30783517, 2019). "For example, the induction of interleukin (IL)-6, IL-10, and CSF-1 contributes to the proliferation and invasion of tumor cells, whereas the secretion of pro-inflammatory IL-1β enhances the antitumor immune response." (PMID 31455032, 2019). "IL-17, serving as a protumorigenic factor, is capable of upregulating the expression of IL-6 and G-CSF as well as energizing the recruitment of neutrophils into the tumor immune microenvironment." (PMID 30944838, 2019). "These tumor epithelial cells showed higher expression of IL11 mRNA transcript when compared to that of IL6." (PMID 30885958, 2019). "IL-6 displays pleiotropic functions, being both pro-inflammatory and immunosuppressive by interacting with the surrounding stroma of tumours." (PMID 31226168, 2019). "The IL-6/STAT3 pathway regulates a number of gene expressions such as Bcl-2 that mediate proliferation or inhibit apoptosis during tumor formation." (PMID 31361777, 2019). "Our results demonstrate that coculture with H-1299 tumor cells leads to the upregulation of IL-6, IL-10, and IL-27 production by CD1c+ DCs compared with that by CD1c+ DCs that were not cocultured with H-1299 cells." (PMID 31921114, 2019). "Activated TAMs contribute to tumor progression by producing pro-inflammatory cytokines, such as IL-6, thus inducing a wide variety of genes involved in tumor progression and apoptosis suppression." (PMID 31591367, 2019). "These cells can then subsequently be differentiated into potent immunosuppressive MDSCs by IL-6 within the tumor microenvironment." (PMID 31781510, 2019). "Further analysis showed that elevated level of IL-6 was positively correlated with elevated Cyr61 level, suggesting a synergistic effect between them in the development of tumor inflammation microenvironment." (PMID 31766991, 2019). "IL-8 and IL-6, which we confirmed to be secreted by 8505C tumor cells (~20 ng/ml/24 h for IL-8 and ~2 ng/ml/24 h for IL-6 in tissue culture), closely reflected the change in tumor burden." (PMID 31337787, 2019). "The tumor suppressive effect of TSLNC8 is due to inactivation of the interleukin-6 (IL-6)/STAT3 signaling pathway." (PMID 31466358, 2019). "At the same time, the lung metastasis in groups treated with IL-6 was slight increased, which was consistent with the tumor promotion effect of IL-6 in SPC-A-1 subcutaneous xenograft cancer model." (PMID 30805774, 2019). "Heat shock protein 90α (HSP90α) on the surface of TRAPs from malignant effusions of cancer patients and tumor cell lines stimulated CD4+ T cell production of IL-6 via a TLR2–MyD88–NF-κB signal cascade." (PMID 31300052, 2019). "A20-silenced DCs inhibited regulatory T cells (Tregs), T helper (Th) cells as well as hyperactivated tumor-infiltrating cytotoxic T lymphocytes that produced interleukin-6 (IL-6) and TNF-α13." (PMID 31308453, 2019). "In the tumor microenvironment, a variety of inflammatory mediators, such as cytokines (IL-6, IL-10, VEGF, TNFα, and TGFβ), chemokines (CCL20 and CXCL8) as well as lipid mediators (such as PGE2) are continuously produced." (PMID 31100828, 2019). "Compared with the ER+BCC-NAF organoid co-cultures, the tumor-associated CD45+CD31+ cells secrete 5.7 ± 0.48-fold more IL1β, 1.5 ± 2-fold CCL7, 1.2 ± 0.2-fold IL6, and 1.1 ± 0.02-fold IL8." (PMID 31419632, 2019). "Enhanced levels of IL-6 were found in three patients with cardiac myxomas and removal of the tumor abolished the IL-6 levels." (PMID 31795299, 2019).
tumor (continued). "It has been shown that Protein S activation of either MerTK or Tyro3 inhibits LPS and IFN-γ induced M1 polarization of peritoneal and tumor-derived mouse macrophages, indicated by decreased expression of M1 marker genes Il1, Il6, Cd86 and Tnf." (PMID 31088471, 2019). "Initial studies demonstrating that blocking IL-6 or IL-11 in HCC reduces tumor burden in mice have recently been published, and these encouraging first results now must be confirmed and translated into the clinic." (PMID 31683891, 2019). "GM-CSF was demonstrated as a critical factor to maintain the myeloid cell viability in cancer, and IL-6 was shown as the most potent proinflammatory cytokine linked to MDSC accumulation and consequent tumor progression." (PMID 30936876, 2019). "High-density tissue also disaplayed increased IL-6 and IL-4 secretion, thereby suggesting pro-tumour Th2 polarization." (PMID 31527531, 2019). "Tumor cells showing BRAF V600E mutation tend to have increased cytokine secretion such as that of interleukin (IL)-1β, IL-6, and IL-8, because cytokines such as tumor necrosis factor alpha or IL-1β increase ATX and LPA levels." (PMID 31455351, 2019). "Pro-inflammatory cytokines, such as TNFα and IL-6 secreted in the tumor microenvironment by immune cells or tumor cells, can drive tumor plasticity and increase cancer stem cell maintenance, as observed in numerous malignancies including GBM2." (PMID 30854231, 2019). "Expression levels of PKM2, SHMT2, and HIF-1α, together with interleukin 6, were also analyzed utilizing normal and tumor FFPE tissues." (PMID 31500219, 2019). "Despite their high cytolytic activity, hypoxic CAR-T cells produced relatively low levels of granzyme B, IFN-γ, IL-2, and IL-6 in response to transfected cells and tumor cell lines endogenously expressing the target antigen." (PMID 31052261, 2019). "IL-6 is produced by numerous cell types located within the tumor microenvironment, and it acts directly on tumor cells to mediate STAT3 tyrosine phosphorylation and induce the expression of STAT3 target genes." (PMID 30857539, 2019). "CAFs are the primary source of IL-6 in the tumor microenvironment of GC, and CAF-produced IL-6 activates the Jak1-STAT3 pathway in GC cells via paracrine signaling, resulting in the development of chemotherapeutic resistance." (PMID 30927911, 2019). "CAF secretion of CXCL12/SDF1, M-CSF/CSF-1, IL-6, and CCL2/MCP-1 recruits tumor-associated macrophages (TAM) to the TME and actively differentiates TAMs into an M2 immunosuppressive phenotype." (PMID 31058816, 2019). "The IL-6/PGE2-positive feedback loop between IRISOE TNBC tumor cells and MSCs enhances tumor aggressiveness." (PMID 31014367, 2019). "A high-affinity anti-IL-6 antibody, MEDI5117, has been shown to enhance the anti-tumor efficacy of chemotherapy in several types of tumors that are known to be driven by the IL-6–STAT-3 signaling." (PMID 31108941, 2019). "Accordingly, IL-6 inhibition in ADSCs significantly antagonized the tumour-promoting effects of these cells." (PMID 31196220, 2019). "Cytokines such as IL6 promote tumor initiation by elevating intracellular reactive oxygen species (ROS) and reactive nitrogen intermediates (RNI) as well as causing epigenetic alteration of certain genes." (PMID 30847302, 2019). "Tumor formation in this model appears to require IL-6, as this can be substituted for IL-33, and tumor formation is completely eliminated in IL-6 knockout mice." (PMID 30815737, 2019). "The suppression of IRS1 and the activation of IL-6 are both reported to induce or promote tumor metastasis." (PMID 30741955, 2019). "IL-6 was correlated with tumor size, number, and metastasis and was an unfavorable prognostic indicator in HCC." (PMID 31751357, 2019). "M2 type macrophages activate secretion of interleukin 6 (IL-6), TGF-β and interleukin 10 (IL-10), and VEGF to enhance tumor growth which are associated with a worse prognosis." (PMID 31579438, 2019).